ENO1 (enolase 1)
Diseases named in the same sentence as ENO1 in open-access papers (continued):
Sharing a sentence is not in itself a finding about the gene and the disease.
tumor (378 papers, 2005 to 2026). "Collectively, the available literature indicates that ENO1 is closely associated with malignant progression through its involvement in metabolic reprogramming and broader tumor-promoting cellular functions." (PMID 42196455, 2026). "Extracellular enolase-1 (ENO1), including membrane-associated and secreted forms, has been implicated in tumor progression; however, its role in cancer-associated fibroblast (CAF)-associated stromal reprogramming in MM is unclear." (PMID 42122262, 2026). "The depletion of CD8+ T cells significantly improved the growth of ENO1-KO tumors, highlighting the contribution of tumor-intrinsic ENO1 deficiency in promoting antitumor immunity via modulation of CD8+ T cell infiltration levels in the tumor microenvironment." (PMID 40665335, 2025). "Depletion of these cells strongly impaired the effect of the ENO1‐DNA vaccine in limiting tumour growth and improving survival in IL17A‐deficient mice, while in IL17A+/+ mice, the role of CD4+ T cells was much more crucial." (PMID 40831074, 2025). "A prognostic risk model incorporating NUP37, PGM2L1, and ENO1 effectively predicted patient outcomes, highlighting these genes’ roles in tumor progression." (PMID 40507914, 2025). "(2021) highlight the importance of ENO1 subcellular relocation in cancer pathogenesis and inflammatory processes, associating these changes with increased tumor aggressiveness." (PMID 41179678, 2025). "Enolase-1 (ENO1), a glycolytic enzyme involved in cellular energy homeostasis, has been widely associated with tumor progression and metabolic adaptation in malignant neoplasms." (PMID 41179678, 2025). "In its extracellular state, ENO1 can be found associated with extracellular vesicles (EVs) or as a soluble protein, promoting intercellular communication and contributing to tumor progression." (PMID 41179678, 2025). "Surface-expressed ENO1 acts as a plasminogen receptor implicated in tumor cell invasion and metastasis." (PMID 40573960, 2025). "ENO1 is frequently upregulated in various tumour tissues and often associates with unfavourable prognostic outcomes." (PMID 39245797, 2024). "First, through the TCGA-BLCA and GSE13507 data, we found that ENO1 expression was upregulated in tumor tissue and positively associated with poor prognosis." (PMID 38273010, 2024). "This was unexpected, considering that ENO1 overexpression is believed to be tumour associated, and MDS by definition contains significantly lower blast numbers compared to AML." (PMID 38473245, 2024). "Another example of a genomic region that was altered in our tumor, corresponds to that encoding the α-enolase (ENO1) gene." (PMID 39239354, 2024). "Another study showed that both human and mouse tumor-infiltrating CD8+ T cells have deficiencies in glycolysis metabolism due to ENO1 dysfunction." (PMID 39657666, 2024). "The analysis of the tumor immune microenvironment by bulk RNA-seq and scRNA-seq showed that ENO1 was associated with CD8+ T-cell exhaustion." (PMID 38273010, 2024). "ENO1 has been found to be overexpressed in a variety of cancers and is associated with tumor cell proliferation and metastasis." (PMID 39457014, 2024). "The results of the clinical correlation analysis of ENO1 gene expression suggest that ENO1 is associated with tumor size and stage." (PMID 38097352, 2023). "ENO1 and related antibodies can reference as underlying biomarkers in the diagnosis and prognosis of tumor." (PMID 37731842, 2023). "High ENO1 expression was closely associated with histological differentiation and tumor invasion in 84 PDAC cases (P < 0.05)." (PMID 36476328, 2022). "Overexpression of ENO1 on a myriad of cancer types together with its localization on the tumor surface makes it a great prognostic and diagnostic cancer biomarker as well as an accessible oncotherapeutic target." (PMID 35434271, 2022).
tumor (continued). "In summary, ENO1 promotes cellular functions associated with tumor progression, including accelerated glycolysis, cancer cell proliferation, migration, invasion, drug resistance, and activation of oncogenic signaling pathways." (PMID 35434271, 2022). "In some cancer patients, increased expression of ENO1 is often accompanied by the production of anti-ENO1 autoantibodies, making the protein a tumor-associated antigen." (PMID 36620599, 2022). "ENO1-deficient tumor cells highly uptake Glc, causing for the PPP or the polyol pathway (PP), characteristic for the decreased lactate levels." (PMID 36077431, 2022). "Here, we showed for the first time that the anti-tumor capability of BM CM was linked to the regulatory network of Hsp90ab1, Eno1, Ubc, CD44, and LAP-TGFβ." (PMID 34830748, 2021). "Patients with both high ENO1 plasma concentration and score in tumor tissue, had a positive association with tumor stage and poor prognosis." (PMID 33804240, 2021). "During hypoxia, changes in enolase-1 abundance and other enzymes in the glycolytic pathway causes tumour cells to respond to the energy demand, which enhances survival and proliferation, and enhance the aggressive and advanced ability of the cells." (PMID 34571787, 2021). "The same effect was observed in tumor-bearing mice treated with anti-ENO1 mAb or injected with adeno-associated virus expressing anti-ENO1 mAb." (PMID 33804240, 2021). "Acetylation lysine residue 335 of ENO1 by histone deacetylase 11 (HDAC11) causes loss of ENO1 activity and suppress the glycolysis in tumor cells." (PMID 34671213, 2021). "ENO1 is expressed on the surface of tumor cells and promoted tumor cells invasion, which has diagnostic and prognostic value in many cancers." (PMID 34530829, 2021). "ENO1 is activated by various glucose transporters and glycolytic enzymes associated with cell cycle progression and the Warburg effect in tumor cells." (PMID 33226369, 2020). "ENO1 expression was significantly associated with the tumor-node-metastasis (TNM) stage and differentiation grade." (PMID 33184263, 2020). "This increased expression is usually accompanied by the generation of anti-ENO1 autoantibodies in some cancer patients, making this protein a tumor associated antigen." (PMID 33584813, 2020). "Proof-of-principle studies were conducted on tumors bearing homozygous deletions of the 1p36 tumor suppressor locus, which results in loss of the enzyme Enolase 1 (ENO1)." (PMID 31324042, 2019). "Aberrant expression of ENO1 has been associated with multiple tumor progression both in vitro and in vivo and higher levels of ENO1 has been correlated with poor prognosis." (PMID 31416219, 2019). "In previous studies, we have demonstrated the presence of T cells specific for the PDA-associated antigen ENO1, both in the tumor and in the blood of PDA patients." (PMID 29462900, 2018). "ENO1, indeed, is different from the “neo-antigens” that represent individual tumor mutations and that require a personalized immunotherapy approach." (PMID 29462900, 2018). "The overexpression of ENO1 is associated with tumor development through a process known as Warburg effect." (PMID 27906678, 2017). "Many metabolic enzymes, including ENO1, are known to interact with cytoskeletal proteins (e.g., F-actin, tubulin), and these associations provide ATP to promote the migration of tumor cells." (PMID 28086938, 2017). "In the present study, the ENO1 rs2274971G allele, which exhibited significantly higher promoter activity compared to the rs2274971A allele, was associated with better survival outcomes, suggesting that ENO1 has a potential tumor suppressor function." (PMID 27767175, 2016). "PGAM1 and ENO1 repression produce a decrease in the glycolytic flux associated with a reduction of tumor growth." (PMID 26918450, 2016). "The levels of TGF-β appear to be higher in the culture containing tumor-associated Treg cells and ENO1-specific CD4+ T cells as compared to that containing OVA-specific CD4+ T cells." (PMID 26551021, 2015).
tumor (continued). "To investigate the prognostic value of ENO1 expression in EC, we assessed the association between levels of tumor ENO1 expression and patients' survival using Kaplan-Meier analysis with the log-rank test." (PMID 25951350, 2015). "To evaluate the influence of tumor-associated ENO1 on the level of anti-ENO1 Ab, we examined the association between ENO1 expressed in the tumor and anti-ENO1 Ab in the blood from the same patients before surgery." (PMID 26551021, 2015). "There is no statistical difference in patients with a higher (≥12%) or lower (<12%) increase of anti-ENO1 Ab after surgery with regards to gender, histological subtypes, pTNM stages, tumor volumes, or EGFR mutation status." (PMID 26551021, 2015). "Since the ENO1 promoter contains a hypoxia responsive element, the overexpression of ENO1 is associated with tumor development through a process known as aerobic glycolysis or the Warburg effect." (PMID 24650096, 2014). "In our previous research, we identified ENO1 as a tumor-associated antigen in NSCLC patients and observed its expression on the surface of cancer cells." (PMID 23894455, 2013). "However, a more intense and heterogeneous staining was observed in malignant tumors, suggesting a possible association between ENO1 overexpression and the aggressive behavior of these neoplasms." (PMID 41179678, 2025). "Previous studies have implicated ENO1 in tumor progression via the PI3K/AKT pathway." (PMID 40730815, 2025). "This suggests that ALDOA/ENO1 may influence the survival of GC patients by affecting the infiltration of tumor-associated macrophages (TAMs)." (PMID 41049005, 2025). "Immediately after this, we constructed a tumor BM model by generating stable ENO1 knockout C4‐2B cells, followed by transfection with ENO1 plasmids carrying different site‐specific mutations, and subsequently injecting the cells into the tibia of BALB/c‐nu mice." (PMID 39563492, 2025). "ENO1 is a glycolytic enzyme that catalyzes the conversion of 2-phosphoglycerate to phosphoenolpyruvate in the glycolytic pathway and is frequently overexpressed in tumor cells in association with cancer progression." (PMID 40775002, 2025). "Notably, extracellular ENO1 and its downstream metabolite S1P synergistically polarized tumor-associated macrophages (TAMs) toward an M2-like phenotype, fostering an immunosuppressive tumor microenvironment (TME) and conferring chemoresistance." (PMID 41353343, 2025). "Concisely, overexpression of ENO1 was found associated with poor prognosis in multiple tumor types." (PMID 36845730, 2023). "Furthermore, the levels of global m6A and ENO1 were both associated with tumor stage progression in LUAD." (PMID 35078505, 2022). "Finally, passenger deletion of enolase 1 (ENO1) is associated with homozygous deletion of the 1p36 tumor-suppressor locus, which provides selective vulnerability to a potent prodrug of the competitive ENO2 inhibitor, POMHEX." (PMID 36358940, 2022). "Taken together, our results indicated that ENO1 might serve as a promising prognostic biomarker for prognosticating prognosis associated with the tumor immune microenvironment, suggesting that ENO1 could be a potential immune-related target against BLCA." (PMID 35836227, 2022). "Together, these findings indicated that ENO1 might function as a crucial regulator in tumor immunity, as well as a potential biomarker associated with immune infiltration in BLCA." (PMID 35836227, 2022). "Because ENO1 is a key enzyme in glucose metabolism, we attempted to explore whether ENO1-regulated tumor cell growth and drug resistance is associated with glucose metabolism." (PMID 36620599, 2022). "The upregulation of ENO1 has been reported in BC and is associated with tumor aggression." (PMID 34312368, 2021). "FAK deficiency resulted in lower ENO1 levels, delaying the in vivo tumor growth." (PMID 33804240, 2021).
tumor (continued). "Besides, our studies implicated that elaboration of the tumor-promoting action of ENO1 will lead to a better understanding of mAb 12C7-mediated anti-tumor mechanisms." (PMID 33579362, 2021). "Moreover, ENO1 expression is associated with the tumor-node-metastasis (TNM) stage, differentiation grade and poor prognosis in HCC patients." (PMID 33184263, 2020). "ENO1 localization on the surface of cancer cells also provides an excellent opportunity to develop small molecules with high affinity to this protein, which enables its direct targeting in the tumor surface for diagnostic imaging and therapeutics." (PMID 33584813, 2020). "Overexpression of ENO1 is associated with tumor progression and invasion." (PMID 27684953, 2016). "Firstly, necrosis of tumor cells under hypoxic conditions during tumor growth may release cell-associated proteins such as ENO1." (PMID 26551021, 2015). "However, Lomnytska found that the expression level of ENO1 was markedly reduced, and was associated with favorable prognosis in EC, suggesting ENO1 functions as a tumor suppressor in EC." (PMID 25951350, 2015). "It is tempting to speculate that the increase in glucose uptake and elevated proliferation rates associated with the in situ tumor growth may provoke a rapid consumption of ENO1, the master regulator of tumor metabolism, and in turn an aberrant release of the enzyme." (PMID 33628097, 2021). "In addition, ENO1 located in the cytoplasm may be associated with the cytoskeleton system and other metabolic enzymes to facilitate tumor cell movement." (PMID 29483925, 2018). "qRT-PCR analysis revealed markedly higher ENO1 levels in A549 and H1299 compared with the normal bronchial epithelial cell line BEAS-2B, consistent with its tumor-associated expression pattern in patient samples." (PMID 41514669, 2026). "Complementary expression profiling demonstrated that ENO1 was significantly upregulated across a wide range of malignancies—including LUAD—reinforcing its potential role in tumor biology." (PMID 41514669, 2026). "Future research will therefore aim to further investigate the molecular mechanisms by which ENO1 contributes to tumor immune evasion." (PMID 40665335, 2025). "In vivo experiments also showed the SPP1 expression was significantly downregulated in ENO1-KO tumor tissues." (PMID 40665335, 2025). "According to both the LinkedOmics database and the GEPIA database, there was a positive correlation between ALDOA and ENO1 in both tumor and normal tissues." (PMID 41049005, 2025). "Mechanistically, circFUT8 facilitates the M2 polarization of TAMs by interacting with ENO1 in the tumor cells." (PMID 41328768, 2025). "Given that ENO1 is highly expressed on the plasma membrane of tumor cells, is detectable in circulation, and is functionally independent of upstream genetic alterations, it represents a promising and broadly applicable target for cancer therapy." (PMID 41168198, 2025). "Enolase 1 (ENO1), a key enzyme in glucose metabolism, is frequently overexpressed in various cancers and plays a crucial role in tumor progression." (PMID 40248198, 2025). "Zhu reported that a MYC-responsive lncRNA called gLINC enhances cancer glycolysis and tumor formation by assembling glycolytic enzymes such as ENO1 and PGK1, PKM2, and LDHA." (PMID 41361062, 2025). "In our study, in vivo genome-wide CRISPR screening and RNA-seq for clinical BC tissues identified ENO1 as a regulator of antitumor-tumor immunity and sensitivity to anti-PD-L1 therapy." (PMID 40665335, 2025). "Ubiquitin-mediated degradation of MYC diminishes its binding to the ENO1 promoter, thereby reducing ENO1 transcription and suppressing glycolysis in tumor cells." (PMID 39980052, 2025). "There is growing evidence that ENO1 is a multifunctional tumor-related protein besides its primary function in glycolysis, and is involved in a variety of physiological processes, including growth control, hypoxia tolerance and autoimmune activity." (PMID 39828712, 2025).
tumor (continued). "Subsequently, phosphorylated ENO1 is linked to the SH2 domain of GRB2 protein, thereby activating the downstream MAPK signaling pathway and triggering tumor proliferation." (PMID 39563492, 2025). "The role of ENO1 in cancer has been well-established, with studies showing that its overexpression promotes tumor progression, angiogenesis, and resistance to ferroptosis." (PMID 41451236, 2025). "We validated the involvement of YWHAZ in the ENO1-mediated tumour-protective mitophagy and drug resistance, and performed rescue assays." (PMID 39828712, 2025). "Silencing circFUT8 reversed these effects by suppressing ENO1 and M2 polarization, inhibiting tumor progression." (PMID 41328768, 2025). "For instance, ENO1 supports tumor survival in nutrient-deprived TME by promoting angiogenesis and sustaining glycolytic activity." (PMID 39920655, 2025). "In contrast, NSUN2 stabilizes ENO1 mRNA via m5C modification, enhancing glycolysis and lactate production and thereby promoting tumor stemness in CRC." (PMID 40859309, 2025). "Overall, our study reveals the molecular mechanism by which osteoblast‐secreted ECM1 in the bone microenvironment under anti‐androgen therapy pressure drives tumor resistance through the ECM1/ENO1/MAPK signaling axis in BMPC." (PMID 39563492, 2025). "For instance, NEAT1 promotes breast cancer progression by forms a scaffold bridge for the assembly of PGK1/PGAM1/ENO1 complexes, yet other studies describe tumor-suppressive functions of NEAT1 in different contexts." (PMID 41361062, 2025). "Our results demonstrate the presence of ENO1 in all tumor samples analyzed, with a predominance in malignant tumors." (PMID 41179678, 2025). "In vivo experiments demonstrated that overexpression of SPP1 in ENO1-KO cells increased tumor volume and weight compared to ENO1-KO tumors (Additional file3P-R) and reduced the abundance of CD8+ T cells, IFN-γ+ CD8+ T cells, and GZMB+ CD8+ T cells." (PMID 40665335, 2025). "Western blot analysis confirmed that ES treatment elevated the levels of Histone H4, Hspa8, MSN, Eef2, Aldoa, and Eno1, which is consistent with previous studies demonstrating Eno1’s tumor-suppressive function." (PMID 39940798, 2025). "Methyltransferase-like 3 (METTL3) regulates tumor metabolic reprogramming by controlling the expression of glucose transporters (GLUTs), lactate dehydrogenase (LDHA), and enolase 1 (ENO1) in tumor cells." (PMID 40046061, 2025). "This immune response elicited by the citENO1 vaccine delayed tumor growth compared to that elicited by unmodified ENO1 peptides." (PMID 40573960, 2025). "Our findings position anti-DCDC2 autoantibody as a promising diagnostic biomarker for ICC, associated with poor prognostic outcomes, and elucidate its critical role in tumor growth and immune evasion through its interaction with ENO1." (PMID 40533767, 2025). "The study demonstrates that circUBE2G1-99aa is downregulated in GC and suppresses tumor progression by binding to the catalytic TIM barrel domain of ENO1, thereby inhibiting its enzymatic activity and glycolysis." (PMID 40730815, 2025). "This is supported by recent findings that glycolytic enzymes, such as enolase-1 (ENO1) exhibit moonlighting functions that actively contribute to tumor progression." (PMID 40933559, 2025). "Beyond its metabolic role, ENO1 exhibits oncogenic functions, acting as a plasminogen receptor on tumor cell surfaces to promote cancer cell proliferation, migration, invasion, and metastasis." (PMID 40734168, 2025). "We carried out a cluster analysis based on the expression of ALDOA/ENO1 in tumor and normal tissues." (PMID 41049005, 2025). "Metabolomic data analysis and quantification of related metabolites demonstrated that ENO1 knockdown markedly suppressed lactate production and intracellular ATP levels in tumor cells." (PMID 41168198, 2025). "Our study reveals a novel mechanism by which ENO1 shapes the tumor immune microenvironment (TIME) in GBM through promoting macrophage polarization." (PMID 41353343, 2025).